IFITM1 (interferon induced transmembrane protein 1)
Description:
IFN-induced antiviral protein which inhibits the entry of viruses to the host cell cytoplasm, permitting endocytosis, but preventing subsequent viral fusion and release of viral contents into the cytosol. Active against multiple viruses, including influenza A virus, SARS coronaviruses (SARS-CoV and SARS-CoV-2), Marburg virus (MARV), Ebola virus (EBOV), Dengue virus (DNV), West Nile virus (WNV), human immunodeficiency virus type 1 (HIV-1) and hepatitis C virus (HCV). Can inhibit: influenza virus hemagglutinin protein-mediated viral entry, MARV and EBOV GP1,2-mediated viral entry and SARS-CoV and SARS-CoV-2 S protein-mediated viral entry. Also implicated in cell adhesion and control of cell growth and migration. Inhibits SARS-CoV-2 S protein-mediated syncytia formation. Acts as a positive regulator of osteoblast differentiation. In hepatocytes, IFITM proteins act in a coordinated manner to restrict HCV infection by targeting the endocytosed HCV virion for lysosomal degradation. IFITM2 and IFITM3 display anti-HCV activity that may complement the anti-HCV activity of IFITM1 by inhibiting the late stages of HCV entry, possibly in a coordinated manner by trapping the virion in the endosomal pathway and targeting it for degradation at the lysosome.
Synonyms: DSPA2a; CD225; IFI17; 9-27; LEU13
Tractability: Antibody: UniProt places it where antibodies can reach, with high confidence; its Gene Ontology location is reachable by antibodies, with high confidence; UniProt predicts a signal peptide or a membrane-spanning region. PROTAC: ubiquitination databases record sites on it.
Gene: Protein-coding gene on chromosome 11 (310,041 to 315,273, forward strand). Ensembl gene ENSG00000185885.
Subcellular location: Cell membrane; Lysosome membrane
Subcellular location (Human Protein Atlas): Golgi apparatus; Plasma membrane
Pathways (Reactome):
Immune System: Immunoregulatory interactions between a Lymphoid and a non-Lymphoid cell; Interferon alpha/beta signaling
Gene Ontology:
Molecular function: protein binding
Biological process: host-mediated suppression of symbiont invasion; negative regulation of cell migration; negative regulation of cell population proliferation; negative regulation of viral genome replication; positive regulation of osteoblast differentiation; response to interferon-alpha; response to interferon-beta; response to type II interferon; response to virus; cell surface receptor signaling pathway; defense response to virus; type I interferon-mediated signaling pathway
Cellular component: lysosomal membrane; membrane; plasma membrane; protein-containing complex
Genetic constraint (gnomAD): Loss-of-function variants: 1 observed, 4.09 expected, observed/expected ratio (o/e) 0.24, 90% interval 0.086 to 1.15. That is too few expected variants to judge how well the gene tolerates losing a copy. Missense variants: 116 observed, 153.69 expected, observed/expected ratio (o/e) 0.75, 90% interval 0.65 to 0.88. Synonymous variants: 70 observed, 65.59 expected, observed/expected ratio (o/e) 1.07, 90% interval 0.88 to 1.3.
Homologues: Orthologues: chimpanzee IFITM1 (99% identical), mouse Ifitm2 (61% identical), mouse Ifitm3 (58% identical), rat Ifitm3-ps2 (56% identical), rat Ifitm1 (54% identical), mouse Ifitm1 (53% identical), mouse Ifitm7 (53% identical). Paralogues in human: IFITM3 (70% identical), IFITM2 (69% identical), IFITM10 (35% identical), IFITM5 (30% identical).
Diseases named in the same sentence as IFITM1 in open-access papers:
IFITM1 is named in the same sentence as 148 diseases in open-access papers, as found by Europe PMC text mining. Sharing a sentence is not in itself a finding about the gene and the disease. The quoted sentences say what the papers report.
viral infection (61 papers, 2011 to 2026). "Based on the GeneCards database, IFITM1 is highly associated with several viral diseases and can inhibit multiple infection with other enveloped viruses including coronavirus." (PMID 35601483, 2022). "Further investigation into how IFITM1 affects human susceptibility to viral infection is required." (PMID 30567988, 2019). "Here, we show that two human IFITM proteins known for performing antiviral roles during virus infection, IFITM1 and IFITM3, interact with one another in endolysosomes." (PMID 42262132, 2026). "Taken together, these data revealed that ABHD17A promotes IFITM1 to restrict various virus infections." (PMID 40723864, 2025). "Since IFITM1 inhibits EBV entry, suppressed expression of IFITM1 leads to increased viral infection." (PMID 39868828, 2025). "The NSP3 of PRRSV was demonstrated to induce the proteasome-dependent degradation of porcine intrinsic virus-restriction factor IFITM1 upon the virus infection." (PMID 39466846, 2024). "This is in contrast to IFITM1, which is strongly upregulated by type I and II interferons to play a role in antiproliferation in context of viral infections." (PMID 39872517, 2024). "IFITM1 is a member of a family of interferon-inducible transmembrane proteins that can confer resistance to viral infections, regulate adaptive immunity, and regulate T cell differentiation." (PMID 38853836, 2024). "Although IFITM1 is known to protect uninfected cells from viral infection via blocking virus-cell fusion and opposing entry by many enveloped viruses, IFITM1 also impairs syncytin-mediated fusion." (PMID 37008954, 2023). "The IFN-induced transmembrane protein (IFITM) family includes members (IFITM1, -2, and -3) that protect multiple cell types from viral infections by preventing viral membrane fusion with cells and by inhibiting the syncytialization of infected cells." (PMID 37008954, 2023). "Other host factors that possess crucial roles in the early steps of viral infections have been shown to be prone to demethylation and other post-translational modifications, including IFITM1 and the serine-incorporators (SERINCs)." (PMID 37947646, 2023). "In the early human embryo, Rec is proposed to induce an antiviral state by activating innate immune pathways and increasing the interferon-induced transmembrane protein 1 to inhibit viral infection." (PMID 35891571, 2022). "Together, our results will provide new insights into understanding the functions of IFITM1 against virus infections." (PMID 33767703, 2021). "In viral infections, such as the dengue virus or influenza A virus, IFITM1 at the cell surface or in the early endosomal pathway suppresses virus entry, whereas IFITM3 prevents virus entry in the late endosomal pathway." (PMID 30704088, 2019). "We observed a similar IFITM1 expression profile during early stages of viral infection in human microvascular dermal endothelial cells (HMVEC-d) cells." (PMID 30237526, 2018). "Based on these results, we concluded IFITM1 to alter virus infection at a post-attachment stage of entry." (PMID 30237526, 2018). "First, we quantified the expression levels of IFITM1 in HUVECs induced by H9N2 virus infection or viral particle inoculation using quantitative real-time PCR and western blot." (PMID 29100522, 2017). "Recently, Wysocka group reported that HERV-K element (Rec), which is expressed in early embryogenesis, appears to induce an innate immune response (IFITM1) and protect the host cells from exogenous viral infection." (PMID 28446240, 2017). "Here we used Real-Time PCR and western blot to quantify the levels of IFITM1 induced by virus infection or viral particle inoculation in HUVECs and BEAS-2Bs." (PMID 29100522, 2017). "In this study, we show the ability of host cell novel miR-36 to specifically inhibit KSHV-induced expression of interferon induced transmembrane protein 1 (IFITM1) to limit virus infection of cells." (PMID 29269892, 2017).
viral infection (continued). "Together, our findings highlight the unconventional machinery by which ABHD17A facilitates the S-palmitoylation of IFITM1 to inhibit various viral infections, which also reveals a previously unknown virological function of ABHD17A in innate immunity." (PMID 40723864, 2025). "Our findings may contribute to the understanding unknown functions of IFITM1 and its effects on virus infection." (PMID 37252940, 2023). "Alternatively, AiV may suppress the effects of IFN produced in response to viral infection, such as EV-71 and RV-14, thus allowing steady-state levels of IFITM1 to function." (PMID 37252940, 2023). "Since we found significantly higher expression of Ifitm1 and Iftm2 mRNA in tBHQ fed mice, we assume that this antioxidant is protective against SARS-CoV-2 infection and is associated with higher resistance to viral infection." (PMID 35629310, 2022). "In addition, a growing number of studies have demonstrated that IFITM1 can broadly limit viral infection, particularly at the step of virus entry." (PMID 33767703, 2021). "In addition, the IFITM1 can inhibit virus infections by preventing virus membrane fusion with cells and by inhibiting fusion of infected cells (syncytialization)." (PMID 33585210, 2020). "This is the first reported study describing viral infection in Ifitm1−/− animals." (PMID 30567988, 2019). "Cellular miR-36 in turn inhibits expression of IFITM1 and thus limit virus infection of cells." (PMID 29269892, 2017). "The microarray results showed that both H9N2 virus infection and inactivated viral particle inoculation increase the expression of IFITM1 at transcription level, and the viral particle inoculation induces a higher level (44.75 folds) of IFITM1 than that (8.53 folds) induced by virus infection." (PMID 29100522, 2017). "Genes in this signature code for proteins that are viral infection restricting factors (e.g. Ifitm1, Ifitm3, Gbp7), that protect against cellular or environmental stress (e.g. Abcb1a, Car2, Ern1, Serpina3g) or that regulate immune activation processes (e.g. Fgl2, Anxa1, Havcr2)." (PMID 27883012, 2016). "Overexpression of IFITM1 delayed L1 capsid protein degradation in primary keratinocytes, which may explain an enhancement of virus infection by IFITM1." (PMID 24827144, 2014). "IFITM1‐mediated restriction may be an evolutionarily conserved mechanism protecting both embryos and germ cells from either reinfection of infectious ERVs or exogenous viral infection." (PMID 28781951, 2017). "One family of ISGs is the IFN-induced transmembrane proteins (IFITMs), including IFITM1, IFITM2, and IFITM3, which limits the viral infection by various viruses." (PMID 41465488, 2025). "The top-scoring genes in the network include the members of Interferon Induced Transmembrane Proteins (IFITM1 and IFITM3) followed by MT1E, MT1X, and MT1G and OASL, all essential proteins involved in the innate immune response to viral infection." (PMID 32012164, 2020). "Interestingly, IFITM1/2/3, and TRIM6, common to all four gene sets, were shown to repress viral infection." (PMID 38201278, 2023). "Various studies have demonstrated that ISG15, 2′-5′ oligoadenylate synthase (OAS2), double-stranded RNA protein kinase R (PKR), interferon-induced transmembrane protein 1 (IFITM1), and nitric oxide synthase (NOS) play a crucial role in inhibiting viral infections." (PMID 37256060, 2023). "Consistent with TMPRSS2-dependent plasma membrane fusion, IFITM1 was found to potently and significantly inhibit infection of early-lineage viruses (Wuhan-Hu-1 and VIC) and VOCs Alpha and Delta in both PV and live virus infections." (PMID 36693093, 2023). "Among the upregulated ISGs, 27 ISGs, including IRF1, IRF7, IFITM1, and IFITM3, play antiviral roles in different stages of virus proliferation, thus inhibiting or delaying the process of virus infection by interacting with other proteins or ISGs to form a complex protein–protein interaction network." (PMID 35401515, 2022).
viral infection (continued). "The formation of super-enhancers governing CXCL9/10/11, CCL7/8/13, IFITM1/2/3, OAS1 genes, but not housekeeping genes, was robustly decreased in SAFA mutation cells after virus infection." (PMID 35658050, 2022). "Indeed, module 3 included three IFN-induced transmembrane (IFITM) genes (IFITM1, IFITM2, IFITM3), involved in the restriction of multiple viruses, that were overexpressed in patients with viral infection and positively correlated with severity." (PMID 33765435, 2021). "Mutant IFITM1 proteins that were unable to localize to the plasma membrane did not restrict viral infection." (PMID 30567988, 2019). "Thus, during an innate immune response to viral infection where multiple ISGs including GBP2/5 and IFITM1/2/3 are induced, we might expect to see stronger inhibitory effects." (PMID 36693093, 2023). "Despite high expression, IFITM1, 2 or 3 did not inhibit virus infection." (PMID 24827144, 2014). "Since IFITM1 has broad-spectrum antiviral functions, combined with our previous findings that ABHD16A negatively regulates the antiviral effect of IFITM1 against various viral infections, we were curious whether ABHD17A could regulate IFITM1’s ability to resist other types of viral infections." (PMID 40723864, 2025). "Overexpression of IFITM1, IFITM2, and IFITM3 proteins did not restrict the entry of pseudoparticles carrying arenavirus envelope glycoproteins and live virus infection." (PMID 35283811, 2022). "Strikingly, canonical ISGs such as MX1, IFITM1, and IFI6 were significantly upregulated (>100-fold) in STAG2−/− HT-29 cells compared to their WT counterparts, in the absence of any virus infection." (PMID 29662124, 2018). "Over-expressing IFITM1 significantly enhanced KSHV infection of cells; IFITM3 moderately enhanced KSHV infection while IFITM2 did not alter the viral infection." (PMID 29269892, 2017). "Finally, we found that genes closest to sites with significant negative coefficients for age included IFITM1, IFITM2, and IFITM3, which are interferon response genes that are activated following viral infections, such as the hepatitis C virus." (PMID 39637179, 2024).
COVID-19 (35 papers, 2020 to 2024). A disease caused by infection with severe acute respiratory syndrome coronavirus 2. "Our study investigated IFN-I driven inflammation and found that the IFN-I responsive genes (e.g., ISG15 and IFITM1/2/3, etc.)and associated-GO pathways were enriched in COVID-19 patients with acute necrotizing encephalopathy." (PMID 37848421, 2023). "Using comparative groups of healthy controls (HC) and individuals with coronavirus disease 2019 (COVID-19), we found that low IFITM1 and increased IFITM3 leukocyte expression are distinctive features of pandemic influenza A(H1N1)." (PMID 35708622, 2022). "Relative to WT cells, HIV-CoV-2 infection was approximately 50-fold higher in IFITM1–3 KO cells, indicating that endogenous IFITM proteins restrict SARS-CoV-2 Spike-mediated infection in this cell type." (PMID 33880473, 2022). "It was previously shown that IFITM3 facilitates replication of the seasonal coronavirus hCoV-OC43, while we and others recently showed that SARS-CoV-1 and SARS-CoV-2 infection is inhibited by ectopic and endogenous IFITM1, IFITM2, and IFITM3 from mice and humans." (PMID 33880473, 2022). "We also identified IFN-stimulated, disease-specific genes; for example, XAF1 is specifically upregulated in COVID-19 patients while IFITM1 is specifically upregulated in HIV-1+ patients." (PMID 36992700, 2023). "The proportions of neutrophil states were compared at t1, and this revealed a divergent expansion of IFNactive neutrophils (clusters 2, 4 and 5) marked by IFITM1 expression in COVID-19, which became similar to bacterial ARDS at t2." (PMID 34782790, 2022). "The increased expression of IFITM1 in B cells displays an indication of COVID-19 by our classification rules." (PMID 35928229, 2022). "Gene expression of IFITM1 in neutrophils from patients with COVID-19 at t1 was confirmed by immunofluorescent staining for IFITM1 protein, co-localized with S100A8/9, and typical neutrophil nuclear morphology." (PMID 34782790, 2022). "Western blot analyses showed significant expression of ISG-15 and IFITM-1, in line with proteomic results showing these EPs from the COVID-19 group." (PMID 35842415, 2022). "The inflammatory mediator of EN-RAGE encoded by S100A12 was significantly correlated with COVID-19, and S100A8, S100A9, IRF3, IFI6, IFITM1, and IFITM3 have been reported to elicit autoinflammatory and autoimmune conditions in response to SARS-CoV-2 infection." (PMID 35172892, 2022). "Further analysis showed that IFITM1 was negatively correlated with HR, lymphocyte counts, and glucose levels in our COVID-19 cohort." (PMID 35708622, 2022). "Analyses in the comparative COVID-19 cohort also suggest the possible participation of IFITM1 and IFITM3 in antiviral defenses against SARS-CoV-2." (PMID 35708622, 2022). "OAS1, OAS2, OAS3, IFIT1, IFIT3, IFI44, IFI44L and IFITM1: Current COVID-19 genetic studies incline to analyze those genes together." (PMID 34109284, 2021). "Taken together, our data suggest that, in women with severe COVID-19, IFITM1 and IFITM3 proteins participate in trophoblastic immune response and possibly promote placental protection against SARS-CoV-2." (PMID 34257394, 2021). "They identified neutrophils (IFITM2, IFITM1, H3-H3B, SAT1 and S100A8) and macrophage cluster-1 (CCL8, CCL3, CCL2, KLF6 and SPP1) as the main immune cell subsets associated with severe COVID-19 cases." (PMID 34109284, 2021). "Additionally, elevated expression levels of IFIT3 and other ISGs, such as IFITM1, were observed in neutrophils from COVID-19 patients." (PMID 39664492, 2024). "Finally, analyses in a comparative cohort also identify an induction of IFITM3 expression and correlation of IFITM1 with clinical variables in individuals with severe COVID-19, which deserve further investigation in more extensive studies." (PMID 35708622, 2022).